GSK3B (glycogen synthase kinase 3 beta)
Diseases named in the same sentence as GSK3B in open-access papers (continued):
Sharing a sentence is not in itself a finding about the gene and the disease.
prion disease (6 papers, 2010 to 2025). A transmissible disease that is caused by a protein that is able to induce abnormal folding of normal cellular proteins, leading to characteristic spongiform brain changes, which are associated with neuronal loss without an inflammatory response. "These works reported that PrP106–126 peptide, widely used as a model of prion disease, as well as prion-activated GSK3β, induced as a consequence an increase in tau phosphorylation." (PMID 34065232, 2021). "Alteration of tau, p-tau (Ser396, Ser404, and Ser202/Thr205), GSK3β and CDK5 were either intermediate or consequent events in TSE pathogenesis and proposed the potential linkage of these bioactive proteins with the pathogenesis of prion diseases." (PMID 20356412, 2010).
progressive supranuclear palsy (6 papers, 2016 to 2024). A rare late-onset neurodegenerative disease characterized by supranuclear gaze palsy, postural instability, progressive rigidity, and mild dementia. "Clinical efficacy and tolerability of tideglusib, an irreversible GSK-3β inhibitor, have been tested in patients with progressive supranuclear palsy." (PMID 30965670, 2019). "Similar effects are expected from Tideglusib, a glycogen synthase kinase 3 beta (GSK-3β) inhibitor, not yet FDA-approved, mainly investigated for AD and progressive supranuclear palsy treatments." (PMID 33281605, 2020).
rhabdomyosarcoma (6 papers, 2011 to 2023). A rare aggressive malignant mesenchymal neoplasm arising from skeletal muscle. "In this study, we tested the irreversible GSK3β-inhibitor, tideglusib for in vivo efficacy in patient-derived xenograft models of both alveolar rhabdomyosarcoma (aRMS) and eRMS." (PMID 28968964, 2017). "Furthermore, CCR9-CCL25 axis activates cell-survival signals through Akt and subsequent glycogen synthase kinase-3 beta (GSK-3β) and forkhead in human rhabdomyosarcoma (FKHR) inactivation." (PMID 21539750, 2011).
subarachnoid hemorrhage (6 papers, 2019 to 2025). A serious neurological disorder characterized by intracranial hemorrhage into the subarachnoid space. "Inhibits the activation of microglia and the synthesis of inflammatory factors after SAH; increases the phosphorylation of AKT and GSK-3β; alleviates early brain injury after subarachnoid haemorrhage; and promotes nerve function recovery in rats." (PMID 35566359, 2022). "SC79 inhibits GSK-3β activity by activating AKT for treatment of early brain injury following subarachnoid hemorrhage." (PMID 33529250, 2021). "Another study investigated the role of Akt/GSK3β pathway in acute brain injury after subarachnoid hemorrhage." (PMID 33430188, 2021). "Additionally, MB reduces neuroinflammation after subarachnoid hemorrhage via the Akt/GSK-3β/MEF2D signaling pathway." (PMID 39957615, 2025).
systemic lupus erythematosus (6 papers, 2021 to 2025). An autoimmune multi-organ disease typically associated with vasculopathy and autoantibody production. "H2S donors inhibited the abnormal activation and proliferation of lupus lymphocytes through the Akt/glycogen synthase kinase 3 beta (GSK3β) pathway." (PMID 34035862, 2021). "In MRL/lpr mice, activation of the PI3K/Akt/GSK3β signaling axis is prevented and lupus T cells accumulate in G0/G1 while the number of S phase T cells decreases." (PMID 34434237, 2021). "High-dose MSC transplantation in MRL/lpr mice (the murine model of systemic lupus erythematosus) effectively ameliorated disease activity by inhibiting abnormal activation of Akt/GSK3β signaling pathway of T cells." (PMID 34090507, 2021). "Notably, the selective GSK3β inhibitor TDZD-8 effectively blocked NLRP3/IL-1β activation in peripheral blood mononuclear cells from patients with systemic lupus erythematosus." (PMID 40526103, 2025). "Furthermore, GSK3β contributes to lupus nephritis development in lupus-prone mice, in part through activation of the NLRP3/IL-1β axis." (PMID 40526103, 2025). "This study reveals that high-dose MSC treatment has a negative effect on cell growth of lupus T lymphocytes and could inhibit G1/S transition of abnormal T cells via inhibition of the PI3K/Akt/GSK3β signaling pathway in the abnormal T cells." (PMID 34434237, 2021).
acute respiratory distress syndrome (5 papers, 2017 to 2021). Progressive and life-threatening pulmonary distress in the absence of an underlying pulmonary condition, usually following major trauma or surgery. "The GSK3B inhibitor reduces the production of IL-6, TNFα, IL-17, and IL-1β in the BALF of mice with lipopolysaccharide-induced acute respiratory distress syndrome, thus relieving the lung injury." (PMID 31466385, 2019).
alcohol dependence (5 papers, 2012 to 2025). Physical and psychological dependence on alcohol. "Moreover, induction of alcohol-induced liver disease in rats resulted in increased expression of cytosolic and nuclear β-catenin, phosphorylated GSK3β, and significantly increased gene expression of Wnt2, Wnt7a, and β-catenin target genes." (PMID 35663960, 2022).
Arrhythmia (5 papers, 2016 to 2024). Any cardiac rhythm other than the normal sinus rhythm. "Our phosphorylation data are consistent with these previous studies, as we found that in a model of severe arrhythmia, pretreatment with liver I/R stimulus enhanced GSK-3β Ser9 phosphorylation, which decreased the incidence of SCD and diminished the predisposition to arrhythmias after reperfusion." (PMID 27768739, 2016). "Similarly, we found that in both diabetic rats and non-diabetic rats, RLIPC reduced the incidence of lethal arrhythmias, induced RISK pathway activation (stimulation of ERK1/2, Akt and GSK-3β phosphorylation) and was GSK-3β serine 9 phosphorylation-dependent." (PMID 29768493, 2018). "However, we found SB216763, a GSK-3β inhibitor, nullified the anti-arrhythmic benefits of RLIPC in our rat arrhythmia model, and suppressed RLIPC-induced GSK-3β Ser9 phosphorylation, without affecting GSK-3β Tyr216 phosphorylation." (PMID 27768739, 2016).
astrocytoma (5 papers, 2009 to 2023). "Multivariate analysis revealed that WHO grade, galectin-3 expression, and GSK3B expression were independent prognostic factors for astrocytoma." (PMID 37185758, 2023). "This study aims to validate the correlation between the clinical outcomes and protein expression of galectin-3/GSK3B in astrocytoma." (PMID 37185758, 2023). "Multivariate analysis revealed that GSK3B expression was independent prognostic factors for astrocytoma." (PMID 37185758, 2023). "Immunohistochemistry staining was performed to detect galectin-3/GSK3B protein expression in patients with astrocytoma." (PMID 37185758, 2023). "Immunohistochemical staining of galectin-3 and GSK3B was analyzed to determine the relationship between protein expression and the clinical parameters of patients with astrocytoma." (PMID 37185758, 2023). "Galectin-3 and GSK3B protein expression were significantly positively correlated with the World Health Organization (WHO) astrocytoma grade and overall survival time." (PMID 37185758, 2023). "When analyzing both forms of GSK3β expression in specific astrocytoma types, diffuse astrocytoma revealed 50% (5/10) of the samples with a lack or low levels of pGSK3β-S9 expression, while 70% (7/10) of the samples showed high levels of pGSK3β-Y216." (PMID 34064046, 2021). "Although the proportion of methylated samples was relatively small in each astrocytoma grade, our results showed that methylation of GSK3β decreased with grade." (PMID 34064046, 2021). "In order to determine the character of the GSK3β role in astrocytoma grades II–IV, we examined the promoter methylation of the GSK3β gene and level of expression of active (pY216) and inactive (pS9) form of GSK3β protein." (PMID 34064046, 2021). "Large deletions of the APC gene associated with increased β-catenin levels, together with oncogenic effects of both β-catenin and GSK3β, are clearly involved in astrocytoma evolution." (PMID 34064046, 2021). "Out of 50 analyzed astrocytoma samples of different grades, 41 (82%) had an unmethylated GSK3β gene promoter, while methylation of the promoter region was detected in nine samples (18%), including three AII (30%), three AIII (27%), and three GBM (10.34%)." (PMID 34064046, 2021). "Our findings on DKK1 and DKK3 show the importance of methylation in the regulation of Wnt signaling activity and also indicate pro-oncogenic effects of GSK3β on astrocytoma development and progression." (PMID 34064046, 2021). "A cell culture model was utilized to study the interactions of mutant tau proteins, model Hirano bodies, and GSK3β in human astrocytoma cells." (PMID 24929931, 2014). "The high GSK3β expression in astrocytoma was most probably due to greater necrosis in the GBM, with increased protein degradation." (PMID 19823589, 2009). "In addition, GSK3B protein expression was significantly positively correlated with the World Health Organization (WHO) astrocytoma grade and overall survival time." (PMID 37185758, 2023). "Therefore, galectin-3 and GSK3B were independent prognostic biomarkers in the astrocytoma cases that were studied." (PMID 37185758, 2023). "Therefore, our study aims to validate not only the relationship between the clinical outcomes but also the protein expression of galectin-3 and GSK3B and the correlation between galectin-3 and GSK3B in astrocytoma." (PMID 37185758, 2023). "However, knockdown of GSK3B/galectin-3 inhibited cell proliferation, invasion, and migration of astrocytoma cells and galectin-3 mediated tumor progression by upregulating GSK3B protein expression." (PMID 37185758, 2023). "Both galectin-3 and GSK3B are potential prognostic markers and may be considered as anticancer target genes for astrocytoma therapy." (PMID 37185758, 2023).
astrocytoma (continued). "In the present study, we investigated genetic and epigenetic changes and protein expression levels of negative regulators of Wnt signaling, DKK1, DKK3, and APC as well as glycogen synthase kinase 3 (GSK3β) and β-catenin in 64 human astrocytomas of grades II–IV." (PMID 34064046, 2021). "Therefore, galectin-3 and GSK3B are potential prognostic markers, and their genes may be considered to be anticancer targets for astrocytoma therapy." (PMID 37185758, 2023). "However, the clinicopathological role of GSK3B and galectin-3 in astrocytoma remains unelucidated." (PMID 37185758, 2023). "Therefore, GSK3B is upregulated by galectin-3 in astrocytoma." (PMID 37185758, 2023). "GSK3β mRNA were higher in GBM and astrocytoma patients compared with the control and protein was found to be expressed in the majority of the tumors analyzed." (PMID 19823589, 2009). "In conclusion, our results propose that GSK3B and galectin-3 are involved in important molecular changes that are significantly related to the WHO astrocytoma grade and are independent biomarkers for astrocytoma prognosis." (PMID 37185758, 2023). "Our findings indicate pro-oncogenic effects of GSK3β on astrocytoma development and progression not necessarily connected to the Wnt destruction complex." (PMID 34064046, 2021). "In this study, 64 astrocytoma samples of grades II–IV were analyzed for genetic and epigenetic changes as well as protein expression patterns in order to explore the roles of the Wnt pathway components, such as DKK1, DKK3, GSK3β, β-catenin, and APC in astrocytoma initiation and progression." (PMID 34064046, 2021). "However, the correlation between the protein expression of galectin-3/GSK3B and the clinical parameters of astrocytoma has not been reported." (PMID 37185758, 2023). "In our study, we found that knockdown of GSK3B attenuated cell proliferation, migration, and invasion and inhibited the β-catenin, p-GSK3B ser9, VEGF, and Ki-67 but not cyclin D1 protein expression in astrocytoma cells." (PMID 37185758, 2023).
chronic myeloid leukemia (5 papers, 2016 to 2023). "Spautin-1 (MBCQ) shows potent anticancer activity and improves the efficacy of imatinib mesylate by associating with GSK3β activation-induced apoptosis via inactivating the PI3K/AKT pathway in chronic myeloid leukemia (CML)." (PMID 36034776, 2022). "Axl is a membrane tyrosine kinase isolated from chronic myeloid leukemia cells and alternatively activates RAS/ERK and AKT/GSK3β signaling." (PMID 36739272, 2023).
gastric adenocarcinoma (5 papers, 2019 to 2025). "Our results presented in this study suggest that the combination of 5-FU and BI processes a synergistic effect on proliferative inhibition and apoptosis induction by enhancing the GSK-3β pathway against gastric adenocarcinoma cells." (PMID 39241034, 2024). "Many studies have confirmed that the regulation of PI3K/AKT/GSK-3β plays a vital role in differentiating gastric adenocarcinoma cells." (PMID 39241034, 2024). "The results showed that BI significantly enhanced the sensitivity of gastric adenocarcinoma cells to 5-FU in vitro and in vivo, i.e. proliferation inhibited, apoptosis induced and GSK-3β protein activated." (PMID 39241034, 2024). "Therefore, our results suggest that BI increases the antitumor effect of 5-FU on gastric adenocarcinoma cells, at least partly from an activated GSK-3β signaling pathway." (PMID 39241034, 2024). "We postulate that GSK3B may potentially initiate this pathway to promote lymph node metastasis in gastric adenocarcinoma." (PMID 36520032, 2023).
gastric tumor (5 papers, 2011 to 2022). "In gastric tumors, miR-92, miR-182 and miR-183 expressions were increased in Gsk3b knockout mice." (PMID 31801236, 2019). "In the present study, inhibition of GSK-3β using complementary approaches (i.e. chemical inhibition and constitutively active Akt over-expression) attenuated proton pump expression, a measure of gastric-like differentiation, in the gastric tumor-derived SGC7901 cell line." (PMID 21439087, 2011). "Suppression of UBE2T also inhibits gastric tumor invasion and metastasis via the WNT signal pathway by inhibiting WNT5A and WNT7B, which in turn promotes GSK3B expression, activates β-Catenin, and inhibits the key oncogene c-Myc." (PMID 28427240, 2017). "We analyzed CDK5RAP3, AKT, p-AKT (Ser473), GSK-3β and p-GSK-3β (Ser9) expression in gastric tumor samples and adjacent non-tumor tissues from 295 patients using immunohistochemistry and Western Blotting." (PMID 29540196, 2018). "CDK5RAP3, p-AKT (Ser473) and p-GSK-3β (Ser9) protein levels were detected in gastric tumor tissues and adjacent non-tumor tissues from an additional 86 patients using Western Blotting." (PMID 29540196, 2018). "The protein level of CDK5RAP3 was markedly decreased in most gastric tumor tissues compared with adjacent non-tumor tissues, and the levels of p-AKT (Ser473) and p-GSK-3β (Ser9) were also negatively correlated with those of CDK5RAP3." (PMID 29540196, 2018).
hypertrophic cardiomyopathy (5 papers, 2018 to 2025). A condition in which the myocardium is hypertrophied without an obvious cause. "Treatment of cardiomyocytes with an inhibitor of GSK3-β causes cell proliferation, while genetic ablation of GSK3-β in mice leads to cardiomyocyte hyperproliferation followed by hypertrophic cardiomyopathy." (PMID 37030487, 2023). "Expression of the LS mutant Q510E causing severe hypertrophic cardiomyopathy in infants inhibits the differentiation of P19CL6 cells in cardiomyocytes mostly due to increased Akt/GSK3β/β-catenin activity, and induces hypertrophic cardiomyopathy in mice through mTOR pathway." (PMID 29396779, 2018). "Then, to clarify the underlying signaling pathway regulated by PRMT1 in cardiac remodeling, we screened some potential signaling pathways that were relevant to cardiac contraction and hypertrophic cardiomyopathy, including p-GSK3β/GSK3β, p-ERK/ERK, p-AKT/AKT and NICD/Notch1." (PMID 37951845, 2023). "However, GSK-3β, a serine/threonine protein kinase, plays a significant role in numerous vital biological processes, and deletion of GSK-3β gene impaired synaptic plasticity and memory, leading to hypertrophic cardiomyopathy and even death during embryonic development 54-56." (PMID 31695758, 2019).
infarction (5 papers, 2011 to 2025). A localised pathological necrosis of tissue resulting from obstruction of the blood supply usually by a thrombus, an embolus, or vascular torsion. "The mRNA expression of Gsk3b and Aqp4, as the direct target gene for miR-29a-5p, was decreased in the peri-infarction tissue after intervention with miR-29a-5p agomir." (PMID 40529227, 2025). "Low-dose copper nanoparticles and exercise (swimming, 90 min, 5 days/4 weeks) also significantly prevent infarction through preconditioning and inhibition of GSK-3β." (PMID 36036015, 2022). "Our recent study has demonstrated that both cardiomyocytes and fibroblasts expressed periostin and ablation of periostin suppressed post-infarction myocardial regeneration by inhibiting the PI3K/GSK3β/cyclin D1 signaling pathway, suggesting a proliferating ability of periostin." (PMID 29872491, 2018). "In mice, exercise (48–72% of VO2max for 4 weeks) also reduces infarction size by up to 60% by increasing phosphorylation of kinases such as Akt, ERK-1/2, p70S6K, AMPK, and GSK3β while reducing levels of PTEN." (PMID 36036015, 2022). "We observed increased phosphorylation of GSK3β as well as Akt in PKG1α MSCs after OGD and in PKG1αMSCs transplanted hearts following infarction compared to NullMSCs." (PMID 23536905, 2013).
inflammatory bowel disease (5 papers, 2013 to 2025). A spectrum of small and large bowel inflammatory diseases of unknown etiology. "Blockade of GSK-3β attenuates TLR-mediated excessive proinflammatory cytokines and constitutes a promising therapeutic option for reducing intestinal immune reactions toward the luminal flora in inflammatory bowel disease." (PMID 24349609, 2013).
liver diseases (5 papers, 2018 to 2025). "Glycogen synthase kinase 3 (GSK3) is a multifunctional serine/threonine kinase with two isoforms, GSK3α and GSK3β, that regulate glycogen synthesis and glucose metabolism, with GSK3β being particularly implicated in liver diseases." (PMID 40004939, 2025). "Subsequently, we hypothesized that Slit3 regulated HCC tumor growth through manipulation of the GSK3β/β-catenin pathway which is commonly associated with the development of HCC and other liver diseases." (PMID 29859044, 2018).
malaria (5 papers, 2018 to 2023). Malaria is a serious and sometimes fatal disease caused by a parasite that commonly infects a certain type of mosquito which feeds on humans. "Kaempferol also acts as an inhibitor of glycogen synthase kinase-3β (GSK3β) of the malaria parasite; hence, it blocks erythrocyte invasion by the parasite." (PMID 37233654, 2023). "In contrast, the inhibition of GSK-3β by DBP increases the GSK-3β Ser9 phosphorylation level in the liver of male, six-week-old ICR mice infected with Plasmodium berghei, by which DBP was implicated as a potential malaria treatment in vivo." (PMID 35408690, 2022). "The dual anti-plasmodial and GSK3β-mediated cytokine-modulating activities of quercetin are requisite of its potential as a plant-derived therapeutic in malaria." (PMID 33803419, 2021). "This study is not the first report on a plant-derived compound that can inhibit host GSK3β in malaria-infected animals." (PMID 33803419, 2021). "Quercetin is a potential plant-derived therapeutic for malaria on the basis that it can elicit anti-malarial and GSK3β-mediated cytokine-modulating effects." (PMID 33803419, 2021). "Thus, flavonoids exhibiting GSK3β-inhibitory properties can be exploited for the development of therapies for malaria." (PMID 33803419, 2021). "In addition, inhibition of glycogen synthase kinase-3β (GSK3β) of the malaria parasite has been reported to be a molecular basis of the antimalarial effect of kaempferol." (PMID 30631601, 2018). "H11809 exerted inhibitory activity against human GSK-3β (Hs GSK-3β) and Plasmodiumfalciparum 3D7 (Pf 3D7) malaria parasites." (PMID 35408690, 2022).